INS (insulin)
Diseases named in the same sentence as INS in open-access papers (continued):
Sharing a sentence is not in itself a finding about the gene and the disease.
Insulin resistance (continued). "Insulin resistance and insulin release were assessed by homeostasis model assessment (HOMA) in multiple studies based on fasting plasma glucose (FPG) and fasting serum insulin (FSIN)." (PMID 32260174, 2020). "Metabolic syndrome, obesity and type 2 diabetes are metabolic disorders characterized by the insulin resistance and the impairment in the insulin secretion." (PMID 33746608, 2020). "In most cases of patients with T2DM, insulin signaling is impaired or the cell is insensitive to insulin (insulin resistance)." (PMID 32170854, 2020). "MUO was classified based on two definitions: having 2 or more cardiometabolic RFs, or being insulin resistant determined by a homeostatic model assessment of insulin resistance (HOMA-IR) ≥ 3.16." (PMID 33012284, 2020). "We previously demonstrated that 6 weeks CIH exposure led to insulin resistance in lean mice by durably altering insulin signaling pathway in WAT." (PMID 33324235, 2020). "While the degree of Akt phosphorylation under these experimental conditions suggests insulin resistance in agreement with previous results, we were interested in making a more quantitative assessment of insulin sensitivity in peripheral tissues." (PMID 33097799, 2020). "This series of biological process can inhibit insulin signal transduction and decrease the sensitivity of tissue cells to insulin, resulting in disorder of glycolipid metabolism and increase of blood glucose and lipids level, thus producing insulin resistance." (PMID 33013704, 2020). "Reduced activity of insulin in adipose tissue likely exacerbates systemic insulin resistance by promoting free fatty acids release by adipocytes, ectopic fat deposition, and lipotoxicity." (PMID 32093387, 2020). "PTP1B phosphorylates IRS-1 tyrosine residues, thereby impairing insulin signaling and inducing skeletal muscle insulin resistance." (PMID 32082422, 2020). "The production of inflammatory cytokines through activation of TLR and NLRP3 contributes to the development of insulin resistance by suppressing insulin signaling." (PMID 33519369, 2020). "After two months, fasting blood sugar, two-hour postprandial glucose, blood insulin, insulin resistance index (HOMA-IR), and HbA1c were reduced in patients treated with propolis." (PMID 33383693, 2020). "Insufficient insulin production (in terms of the continuous insulin resistance or failure of beta-cell) leads to an increased concentration of serum glucose." (PMID 33552973, 2020). "To this end, we performed association analyses of plasma metabolites with fasting glucose, fasting insulin, the insulinogenic index, two indices of insulin resistance (HOMA-IR and Matsuda) and HbA1c." (PMID 32124065, 2020). "Insulin resistance is characterized by a diminished response to insulin stimulation, resulting in the failure of target tissues to adequately dispose of blood glucose, inhibit lipolysis, stimulate glycogen synthesis, and inhibit hepatic glucose output." (PMID 33038072, 2020). "The characteristic features of insulin resistance in adipose tissue are intensified lipolysis (normally inhibited by insulin) and an increase in free fatty acids (FFAs) in the plasma." (PMID 32796572, 2020). "Insulin resistance is characterized by the weak sensitivity of insulin in peripheral tissues such as skeletal muscle, adipose tissue and liver, resulting hyperglycemia, hyperinsulinemia and dyslipidemia." (PMID 33240683, 2020). "Insulin resistance is a pathologic condition in which insulin-dependent cells, such as skeletal muscle, liver, and adipocytes stop responding properly to normal circulatory levels of insulin." (PMID 32971975, 2020). "Insulin resistance is defined as an impaired biologic sensitivity and/or responsiveness to insulin stimulation in target tissues including the muscle, adipose tissue, and liver." (PMID 32610588, 2020). "Many works on muscle insulin resistance relate to the role of ceramide accumulation in inducing insulin pathway disorders." (PMID 33036203, 2020).
Insulin resistance (continued). "In this study, the HFD induced features of T2DM in some of the mice, illustrated by elevated fasting glucose and insulin concentrations, and impaired glucose tolerance/insulin resistance as determined by a GTT." (PMID 32260528, 2020). "Glucose tolerance and insulin tolerance tests were conducted to assess the effects of the peptides on insulin resistance." (PMID 31914125, 2020). "T2DM is characterized by insulin resistance and/or insulin secretory dysfunction which can be influenced by vitamin D status." (PMID 32013162, 2020). "We have shown that TXNIP preserves almost full insulin sensitivity by increasing insulin responsiveness of AKT phosphorylation under severe insulin resistance conditions, such as ob/ob mice." (PMID 32824669, 2020). "In obese rats, attenuating increased ceramide levels can ameliorate insulin sensitivity in the hypothalamus and prevent central insulin resistance." (PMID 33329397, 2020). "APN caused a significant decrease (P < 0.05) in weight gained, body mass index, insulin resistance, plasma glucose, and insulin levels." (PMID 33163962, 2020). "In skeletal muscle, hyperinsulinemia and insulin-resistance promotes decreased glucose uptake, increases fatigue, decreases physical activity, and subsequently increases insulin-resistance of muscle tissue." (PMID 32153503, 2020). "Low expression of this gene is related to insulin resistance by interfering lipid oxidation, oxidative stress, and it acts on the regulation of pancreatic insulin secretion." (PMID 32580324, 2020). "Insulin inhibits hepatic glucose output and stimulates lipogenesis in the liver, both of which are reduced in the presence of insulin resistance." (PMID 32158768, 2020). "Those in the fourth quartile of isoflavones had lower levels of insulin and insulin resistance compared to women in the first quartile." (PMID 32824177, 2020). "IRS1 is an important regulator of insulin signaling and the loss of IRS1 leads to insulin resistance." (PMID 33197889, 2020). "The lipoprotein insulin resistance index is an algorithm calculating insulin resistance from six lipoprotein measures (3 subclases and 3 particle sizes) obtained from NMR spectroscopy, associated with both hepatic and peripheral insulin resistance as well." (PMID 32178676, 2020). "The net effect of this coordinated response is the lowering of blood glucose levels, and if this is not achieved then pancreatic β-cells compensate by increasing insulin release resulting in hyperinsulinemia, a key characteristic of insulin resistance." (PMID 32350271, 2020). "Our results showed that the glucose intolerance and insulin resistance were improved in MIFP1G/P1G mice under HFD via enhancing insulin signaling." (PMID 32265835, 2020). "As with IL-6, TNFα levels positively correlate with adiposity, BMI, insulin levels, and insulin resistance." (PMID 32158768, 2020). "Heightened circulating LPS induces iNOS expression which promotes S-nitrosylation of Akt, IRS-1 and insulin resistance, deactivating nodes crucial to insulin signaling." (PMID 32429195, 2020). "Even in the subgroup analysis, the low-dose consumption of CoQ10 (<200 mg/d) effectively reduced the values of FBG, HbA1c, fasting blood insulin, homeostatic model assessment for insulin resistance (HOMA-IR), and TG with high tolerability profile." (PMID 32331285, 2020). "Plasma glucose and insulin levels, as well as homeostatic model assessment for insulin resistance (HOMA-IR), after chronic cannabidiol (CBD) administration in rats fed standard (control group) and high-fat diets (HFD)." (PMID 32859125, 2020). "Insulin resistance was already diagnosed in 38% of patients, with 25% of those prescribed insulin prior to admission." (PMID 32704574, 2020). "Clinical studies revealed patients with phaeochromocytoma had impaired insulin secretion as well as increased insulin resistance." (PMID 33324347, 2020).
Insulin resistance (continued). "Physiologically, insulin resistance is characterized as decreased insulin‐stimulated blood glucose uptake by skeletal muscle and adipose tissue, as well as a failure to inhibit lipolysis and glucose production in the liver." (PMID 32776502, 2020). "BMAL1 knockdown induces insulin resistance, as indicated by markedly impaired insulin-stimulated phosphorylation of insulin receptor and AKT pathway." (PMID 32334629, 2020). "GSNO was able to revert insulin resistance induced by sucrose feeding, in a dose-dependent manner, suggesting that they have an insulin-sensitizing effect in vivo." (PMID 32942712, 2020). "Insulin resistance, involving a defect in insulin secretion, insulin action, or both, is central to the etiology of T2DM." (PMID 33628196, 2020). "The significance of MAMs in insulin resistance has started to be elucidated, and growing evidence supports the involvement of this apposition in maintaining insulin sensitivity by mediating Ca2+ regulation, insulin signaling, and metabolic homeostasis." (PMID 33339212, 2020). "Probiotic yogurt was found to have largely beneficial effects on metabolism and metabolic changes, with moderation of insulin levels, prevention of insulin resistance, and decreased incidence of gestational diabetes." (PMID 32864237, 2020). "Increased peripheral insulin levels results in insulin resistance which itself has large effects on the brain and have been associated with depression." (PMID 32494038, 2020). "Third, metabolic acidosis suppresses adiponectin gene expression and lowers circulating levels of adiponectin, which functions as an insulin sensitizer, and low adiponectin levels were associated with increases in HOMA-IR score and insulin resistance risk." (PMID 33292308, 2020). "In this study, (CA+24-MCA) ameliorated the altered insulin resistance and normalized serum insulin level in diabetic animals." (PMID 32584888, 2020). "Since the mass of muscle, a target organ of insulin, decreases in sarcopenia, patients with sarcopenia have insulin resistance." (PMID 32612097, 2020). "In this study, we found that individuals with a higher dietary composition of starch had significantly lower insulin levels and insulin resistance (estimated by HOMA-IR)." (PMID 33490099, 2020). "A key negative regulator of insulin signalling is protein tyrosine phosphatase 1B (PTP1B) that causes dephosphorylation of activated insulin receptor and induction of insulin resistance." (PMID 32042410, 2020). "In HFD/STZ-induced diabetic animals, the levels of blood glucose and homeostatic model assessment of insulin resistance (HOMA-IR) were significantly increased whereas the levels of plasma insulin were significantly decreased." (PMID 32013797, 2020). "Several mechanisms have been postulated, including the prohypertrophic effects of insulin, insulin growth factor-1, and insulin resistance." (PMID 32032383, 2020). "Metformin improved systemic insulin resistance and increased the hepatic insulin signaling cascade and it lowered both the concentration and FSR of ceramides, DAG, and augmented acylcarnitine content and the expression of mitochondrial markers." (PMID 33133018, 2020). "This led to a consequent improvement on insulin resistance, according to several indicators, such as serum insulin level, fasting blood glucose level, or oral glucose tolerance test value." (PMID 32825758, 2020). "The term ID encompasses insulin resistance (IR), exaggerated insulin response to oral carbohydrates and fasting hyperinsulinemia (HI) and therefore results in either permanent or transient HI." (PMID 32448298, 2020). "Magnesium plays a role in insulin homeostasis, and evidence showed an inverse correlation between insulin resistance and magnesium intake, especially in overweight individuals." (PMID 33269017, 2020). "It is suggested that insulin resistance can be induced by oxidative stress, which impairs insulin signaling." (PMID 32971941, 2020).
Insulin resistance (continued). "The contents of total cholesterol (CH), triglyceride (TG), fast glucose, and insulin (INS) were examined using ELISA, followed by the evaluation of insulin resistance (IR)." (PMID 33123597, 2020). "Consistent with the data from previous studies 29, 30, the insulin tolerance test showed that Egr1-/- mice were protected from diet-induced insulin resistance." (PMID 32226550, 2020). "Beta cell dysfunction initially presents in prediabetes (e.g., in obesity and insulin resistance) through their hypersecretion of insulin in response to elevated glucose concentrations." (PMID 33158303, 2020). "The insulin resistance reduces glucose uptake and the excess glucose triggers a compensatory insulin response." (PMID 33365205, 2020). "Long-term persistence can reduce the levels of fasting blood glucose and insulin and reduce insulin resistance accompanied by the decrease of inflammatory reactions." (PMID 33062003, 2020). "In the present study, we assessed if there is an altered insulin effect in a previously suggested in vitro cell culture model of neurodegeneration and insulin resistance induced by STZ." (PMID 31858268, 2020). "Meanwhile, increased pancreatic IL-1β, IL-6, and IL-8 decrease insulin gene expression in β-pancreatic cells, contributing to increased insulin resistance." (PMID 32903730, 2020). "The imbalance of oxidative stress and antioxidant defenses can potentially reduce insulin sensitivity and increase insulin resistance in peripheral tissues." (PMID 32971941, 2020). "Hypercortisolemia results in increased gluconeogenesis, altered insulin secretion, increased insulin resistance and the presence of DM and metabolic complications." (PMID 32880849, 2020). "Skeletal muscle, which is the main target site of insulin, plays an important role in the development of insulin resistance." (PMID 33362555, 2020). "Studies have shown that PTP1B knockout animal models exhibit increased skeletal muscle insulin sensitivity and reduced insulin resistance." (PMID 32082422, 2020). "Treatment of bisphenol A (BPA)-stimulated insulin resistant HepG2 cells with curcumin (5 μM) for 5 days resulted in significantly attenuated BPA-induced insulin resistance and oxidative stress." (PMID 31906278, 2020). "Hyperglycaemia in pregnancy is widely accepted to result from an imbalance between rising insulin resistance and inadequate insulin secretion, yet specific mechanisms likely differ between, and amongst phenotypic groups." (PMID 32240196, 2020). "All of the subjects were insulin resistant (homeostasis model assessment for insulin resistance; HOMA-IR ≥ 2.5)." (PMID 32916306, 2020). "The role of insulin in the regulation of protein metabolism indicated the adverse effects of insulin resistance and high VFA on muscle protein metabolism in older subjects." (PMID 33198340, 2020). "Increases in blood glucose level, insulin level, and insulin resistance index in PCOS rats indicated that letrozole-induced PCOS rats showed the characteristics of metabolic disorders." (PMID 32733580, 2020). "Studies in non-diabetic participants with obesity using surrogate indices of insulin sensitivity have found that the VLCD resulted in significantly lower insulin resistance as measured by HOMA-IR and improvement in insulin sensitivity using the QUICKI." (PMID 32817749, 2020). "Seven, four and four studies had sufficient data for inclusion in analyses of fasting glucose, fasting insulin, and homeostasis model assessment of insulin resistance (HOMA-IR), respectively." (PMID 32164541, 2020). "Insulin signaling impairment and insulin resistance have been observed in neurodegenerative diseases such as AD and PD." (PMID 33100956, 2020). "Specifically, disrupted MAMs integrity and altered MAMs juxtaposition contribute to insulin resistance through impaired Ca2+ exchange, altered lipid metabolism, and dysregulated insulin signaling molecules." (PMID 33339212, 2020).
Insulin resistance (continued). "To assess the impacts of both hormones on insulin resistance, we surveyed several indexes of insulin sensitivity in the current study." (PMID 32395890, 2020). "The reduced insulin activity, in T2DM or insulin resistance, caused microvascular alterations (in skin, eye, kidney and neurovascular tissues)." (PMID 31963760, 2020). "Adiponectin increases insulin sensitivity and has an anti‐inflammatory effect, which counteracts insulin resistance and low‐grade inflammation." (PMID 31880032, 2020). "In agreement with previous study using the same treatments, showed increased insulin sensitivity, decreased blood glucose levels, and the need for using a homeostatic model assessment of insulin resistance (HOMA-IR)." (PMID 33281368, 2020). "As expected, the S1a/ETP mice showed an increased liver weight/body weight ratio, exacerbated inflammation, and a fibrotic phenotype with insulin resistance, as assessed by fasting blood insulin levels and the GTT and ITT results." (PMID 33110211, 2020). "Adipose tissue inflammation and insulin resistance closely correlate in obese persons and blocking systemic or adipose tissue macrophage inflammation improves insulin sensitivity in obese mice." (PMID 32211075, 2020). "This was emphasized in the current study where measures of postprandial insulin and insulin resistance were higher in South Asians than white Europeans." (PMID 30403772, 2020). "Insulin resistance inobesity is manifested by decreased insulin-stimulated glucose transport andmetabolism in adipocytes and skeletal muscle and by impaired suppression ofhepatic glucose output." (PMID 32999709, 2020). "During pregnancy, significantly higher values of fasting plasma glucose (FPG), 2h OGGT, insulin, and homeostasis model assessment of insulin resistance (HOMA-IR) occurred in GDM patients in comparison to control, as was expected." (PMID 33105558, 2020). "Oral glucose administration leads to increased insulin secretion and compensatory insulin resistance compared with intravenous glucose administration." (PMID 32385603, 2020). "In short, accumulation of lipids in muscles and liver initiates insulin resistance, as ectopic lipids inhibit the actions of insulin such as glucose uptake and inhibition of lipolysis." (PMID 32752028, 2020). "In the present study, EA treatment ameliorated insulin resistance as evidenced by decreasing serum insulin level and HOMA-IR index in PCOS-like rats, which was counteracted by SREBP1 overexpression." (PMID 33109277, 2020). "Whereas p38 MAPK increases insulin-independent glucose uptake and oxidative metabolism in muscles during exercise, it contrastingly mediates insulin resistance and glucose intolerance during metabolic syndrome development." (PMID 32899870, 2020). "Insulin resistance occurs when a given concentration of insulin produces less than the expected effect on target cells, which can lead to impaired glucose intolerance." (PMID 33009367, 2020). "Berberine and pioglitazone significantly decreased the serum fasting insulin level (p < 0.01), and alleviated insulin resistance as shown by the oral glucose tolerance test (p < 0.05) in fructose-fed mice without affecting fasting glucose levels." (PMID 32393087, 2020). "Hininger-Favier and coworkers in 2009 evaluated the antioxidative effects of green tea on insulin sensitivity and found that it markedly improved insulin resistance in diabetic rats." (PMID 32215179, 2020). "Of the 45 obese volunteers, 27 (60%) would be defined as insulin resistant (homeostatic model assessment of insulin resistance>2.017), and 18 (40%) fulfilled the criteria for a diagnosis of nonalcoholic fatty liver disease (>5% liver fat)." (PMID 32138541, 2020). "Under normal physiological conditions and in conditions of insulin resistance, insulin regulates β-cell mass through enhanced proliferation and reduced cell death by apoptosis." (PMID 32150819, 2020).